B2M (beta-2-microglobulin)
Diseases named in the same sentence as B2M in open-access papers (continued):
Sharing a sentence is not in itself a finding about the gene and the disease.
tumor (continued). "IFN-gamma is one of the T cell effector cytokines and is known to help inhibit tumor cell growth by suppressing cell proliferation, facilitating apoptosis in cancer cells, and upregulating tumor antigen presentation on beta-2 microglobulin through the JAK-STAT signaling pathway." (PMID 35582437, 2020). "All 7 nonresponders harbored either JAK1 (6 tumors) or B2M mutations (1 tumor), while only 1 of the 3 responders harbored a JAK1 mutation (Fisher exact test, two-sided P = .067)." (PMID 32494760, 2020). "Indeed, an investigation of tumor tissues illustrated that B2M mutations were frequently present in CRC with microsatellite instability, indicating the existence of B2M mutation in pre-therapy MSI-H CRC." (PMID 32793604, 2020). "However, serum B2M levels also imply involvement of the immune reaction to the tumor because it is a component of major histocompatibility complex (MHC I)." (PMID 32219067, 2020). "Furthermore, we have investigated for the first time 11C-MET PET volume-based biomarkers (TMTV, TMLU) demonstrating a positive correlation with MM serum markers of tumor burden such as M component, bone marrow (BM) infiltration, or B2M." (PMID 32340251, 2020). "FADS3 expression measured against B2M reference gene was lower in the growing tumor area versus the peritumoral area and in the necrotic core versus the peritumoral area, but—similarly to previous genes—the observed differences were not statistically significant." (PMID 32392704, 2020). "However, the expression of B2M is significantly altered in the GBM tumor, and it is significantly different from that in the brain." (PMID 32392704, 2020). "Moreover, it was noticed that the immune response of tumour IM was higher in PD-1+CD8+ TIL ACT group than in the control group: B2m, a component of MHC-I molecules, was elevated in the margin of tumour nest, and there were more PD-L1+ TILs." (PMID 32616847, 2020). "In addition to their high HEV density, B2M-mutant (n = 12) tumours also presented with stronger PD-L1 expression (p = 0.0161, Pearson’s chi-squared test) in comparison with their B2M-wild-type (n = 14) counterparts." (PMID 31358939, 2019). "Cytotoxicity was elevated in both HLA and B2M mutant tumors pan-cancer and in several tumor types." (PMID 31345234, 2019). "The primary mechanism of CD3+ CD8+ T cell activity is mediated through direct contact of the T cell receptor on the CD3+ CD8+ T cell with the MHCI/peptide/B2M complex on tumor cells, while anti-tumor activity of CD3+ CD8- T cells is mediated through both contact dependent and independent mechanisms." (PMID 30651131, 2019). "Importantly, it has been shown that Tα1 increases proteins expression on the surface of tumor cells and arbitrate antigen production such as major histocompatibility class (MHC) I, II, beta-2 microglobulin, and tumor-specific antigen." (PMID 31258535, 2019). "Thus, loss of B2M and defective IFN-γ signaling can contribute to a T cell-resistant phenotype and are tumor-intrinsic determinants of resistance to immunotherapies." (PMID 31703593, 2019). "While the primary tumor was not available for comparison, loss of B2M and MHC-I have been reported as mechanisms of immune resistance." (PMID 31692889, 2019). "NK cell levels were elevated in tumors with B2M mutations pan-cancer, however the levels were not significantly different in any given tumor type." (PMID 31345234, 2019). "Using JAK1/2-KOs cell lines we showed that intratumoral administration of the TLR-9 agonist SD-101 was able to overcome local resistance to anti-PD-1 even in abscopal sites, and the NKTR-214 overcame resistance to anti-PD-1 in the B2M-KO tumor growth and significantly increased survival." (PMID 30400822, 2018). "To determine whether DR-18 was effective in the setting of ICI-resistance, we utilized three tumor models with impaired MHC class I surface expression (RMA/S and Beta-2 microglobulin-deficient MC38 and YUMMER1.7)." (PMID 30400822, 2018).
tumor (continued). "Collectively, our results strengthen our hypothesis that in ESCC, MSCs-derived B2M promotes tumor-initiation and invasion via enhancing EMT, resulting in a poor clinical outcomes for the patients." (PMID 29615660, 2018). "Third, the emergence of HLA-I negative tumor variants by B2M mutations and defects in genes that regulate the IFN-gamma signaling, occurs during the natural history of cancer or after immunotherapy as a result of immune selection." (PMID 29423109, 2018). "Considering the importance of EMT in tumor development, we investigated whether MSCs-derived B2M could influence the EMT process of ESCC cells in vitro." (PMID 29615660, 2018). "Considering that tumor-initiating capability is related to distant metastases, it is logical to further suggest that B2M might be a biomarker and/or drug target of distant metastases of ESCC." (PMID 29615660, 2018). "However, consistent with flow cytometric analysis of marrow isolated from SUM159-inoculated mice, we detected tumor cells by qPCR analysis for human B2M expression in 2/8 (25%) mice and human HPRT1 in 3/8 (38%) mice." (PMID 30250146, 2018). "Our results of in vitro experiments indicated that B2M of MSCs could promote tumor cells acquiring stem cell-like properties, which may enhance their initiating capability." (PMID 29615660, 2018). "The most straightforward reason why tumors would not respond to PD-1/PD-L1 blockade therapy is lack of recognition by T cells via the mechanisms such as absence of tumor antigens, loss of HLA expression, and Dysfunctional mutations in B2M." (PMID 29299180, 2017). "The presence of simultaneous LOH and frameshift B2M mutations in Pat208, along with concurrent loss of B2M and HLA Class I protein expression, suggests that B2M aberrations could contribute to tumor evasion of CD8+ T-cell responses and disease progression." (PMID 29070816, 2017). "Finding from previous studies suggested that serum beta-2 microglobulin might indicate cell turnover rate, high tumor burden and subsequent unfavorable clinical course of cancer." (PMID 27764777, 2016). "Third, could tumor antigen-specific CD4 T cells, or innate cells such as NK cells or myeloid cells, be targeted to promote anti-tumor immunity in tumors harboring B2M mutations?" (PMID 27782862, 2016). "The poor secretion of TGF-β1 in tumour cells may result in low autocrine and exocrine of this cytokine and finally lead to the induction of B2M expression." (PMID 26983758, 2016). "The results of our analysis proved that the expression of reference genes in our cohort of patients, including only endometrioid histotype and carefully selected and balanced according to their tumor grade, was dependent on tumor grade for B2M, GAPDH, H3F3A, GUSB, HPRT1, POLR2A and UBC." (PMID 25473950, 2014). "Ratios of COX-2 mRNA expression in tumor/normal colorectal mucosa, normalized with respect to tissue weight, correlated best with the corresponding ratios normalized for B2M (R = 0.952; P < 0.0001), and to a lesser extent with those normalized for GAPDH (R = 0.830; P < 0.0001)." (PMID 24383454, 2014). "A long-term follow-up study of PPL-DLBCL, the largest known series thus far, noted strong homogeneity among the patients: low clinical risk, early stage, and no bulky tumor mass, normal lactic dehydrogenase and beta 2 microglobulin." (PMID 25273521, 2014). "In the tumour host immune response, HLA-A,B,C assembles with B2M in the endoplasmic reticulum." (PMID 18506145, 2008). "To evaluate the tumor growth inhibitory potential of B1451, we established an H_αvβ3 A375 xenograft model in severely immunodeficient mice (Balb/c-Null for DNA Damage-Growth factor Attenuated Background, Beta-2 Microglobulin Knockout mouse, B-NDG B2m KO mice) mice (n=5)." (PMID 41601637, 2026).
tumor (continued). "Low expression of IL‐11 in tumour cells was associated with significantly higher levels of leukocytes (CD45), T cells (CD3, CD4, CD8), T‐cell activation (CD44, CD25, ICOS, Tim3), dendritic cell activation, antigen presentation (CD11c, CD80, B2M, HLA‐DR) and macrophage (CD68) markers." (PMID 40673604, 2025). "Tumor-infiltrating B cells may downregulate B2M to evade MHC-I-mediated immune surveillance." (PMID 40948800, 2025). "In addition, loss of expression of tumor cells B2m and LMP2, but not Jak1, led to a significant decrease of polymorphonuclear myeloid-derived suppressor cells (PMN-MDSC) infiltrates in the TME." (PMID 38427670, 2024). "Furthermore, when analyzing for potential mutations responsible for tumor immune escape, only in one of the patients with a non-paired acquired resistant tumor lesion, stop-gaining mutations were found in the B2M and PTEN genes." (PMID 38280045, 2024). "Irrespective of the visual separation, the average expression of both B2M and HLA-A was significantly higher on treatment compared to the baseline time point (B2M p~0.045, HLA-A p ~0.018, n=53, one sided t-test), confirming a frequent increase in expression of both proteins on tumor cells." (PMID 38455061, 2024). "Additionally, Western blot analysis demonstrated that BLM elevated B2M expression in tumor samples." (PMID 39106105, 2024). "In a study by Sade-Feldman, the authors analyzed longitudinal tumor biopsies from 17 metastatic melanoma patients and observed that B2M deficiency was more prevalent in non-responder patients (29.4%) compared to responders (10%) treated with anti-CTLA-4 or anti-PD-1 therapy." (PMID 39273605, 2024). "Since the tumor PDL1 status was determined using either with SP142 or SP263 antibody clones, a covariate was added to enable testing for significant association between PDL1 positive staining and likelihood for HLA-A or B2M positive cells (details in M&M section)." (PMID 38455061, 2024). "Besides, serum B2M are also correlated with tumor grade and prognosis of tumor patients." (PMID 38743119, 2024). "We noticed that neither CD8+ T cell depletion nor B2m knockout exhibited full rescue of the tumor growth from Pikfyve-loss, suggesting that Pikfyve-loss may inhibit tumor growth in an immune-independent manner." (PMID 38011559, 2023). "Although inconclusive, numbers of ICI-resistant markers have been proposed for MSI-H tumours, including low TMB, Janus kinase (JAK1/2/3) mutations, loss of beta-2-microglobulin (B2M) that could impair antigen presentation by class I major histocompatibility complex." (PMID 35842545, 2022). "Moreover, we ablated B2m in WHSC1-overexpressing cells to determine whether the tumor-suppressive effects of WHSC1 were dependent on MHC-I upregulation." (PMID 35230972, 2022). "It has also been shown that MSI/dMMR PDACs may have significant intra-tumor heterogeneity and may lead to the development of metastatic MSS PDACs and recurrent beta-2-microglobulin (B2M) gene inactivation, which may be associated with tumor resistance to immune checkpoint inhibitor therapy." (PMID 36231030, 2022). "However, studies of metastatic cell lines and tissue samples have identified the complete lack of HLA class I antigen expression due to B2M gene deficiency as one of several genetic alterations affecting the tumor cells’ immunogenicity." (PMID 36046045, 2022). "The lack of BTG1 and B2M mutations in tumor tissue DNA suggests that ctDNA fragments with these mutations may have originated from distant metastatic tumor tissues with different genotypes in this FL patient." (PMID 35795062, 2022). "However recent studies have also shown that loss of MHC protein expression can occur in HLA or B2M wild-type tumour cells, highlighting the role of non-genetic mechanisms in regulating MHC-I expression." (PMID 35343573, 2022).
tumor (continued). "In contrast to other tumor types, MHC class I expression is associated with a poor prognosis in some MBs, possibly because of ERK activation by incomplete so-called conformer MHC class I molecule expression, deficient of beta-2-microglobulin and/or peptide expression." (PMID 35892842, 2022). "Interestingly, a retrospective analysis of B2M expression and mutation status in colorectal dMMR cancer patients showed favorable clinical outcomes in patient cohorts despite B2M loss-of-function mutations, counterintuitive to the mechanisms of MHC-I dependance of immune-mediated tumor rejection." (PMID 34630437, 2021). "The results showed that the expression levels of B2M and HLA were significantly higher in CA compared with CB, indicating that CB tumor samples may escape immune surveillance through the decreased expression of MHC genes and may partly explain the poor prognoses of CB." (PMID 34212175, 2021). "Loss of heterozygosity and genetic deficiencies of β2-microglobulin (B2M) are both crucial ways that lead to the loss of MHC molecules, which promote resistance to PD-1 blockade due to the inability of CD8+T cells to recognize tumor antigens and specifically kill tumor cells." (PMID 35003090, 2021). "Because a B2M antibody was part of the IMC panel, we could assess that a B2M truncating mutation led to no protein expression in the tumor compared with a widespread B2M expression in CRCs with wild-type B2M." (PMID 34197832, 2021). "Another mutation identified in tumor biopsies of non-responders was the mutation in antigen-presenting protein beta-2-microglobulin (B2M), one of the components of MHC I. This aberration can lead to a loss of surface expression of MHC I and disable a proper CD8+ T-cell recognition." (PMID 32992737, 2020). "Various mutations can result in a lack of tumor-specific B2M, especially a loss of heterozygosity." (PMID 32000802, 2020). "The sole tumor with mutation in B2M was a nonresponder that harbored two B2M mutations previously reported in The Cancer Genome Atlas (TCGA): a B2M c.68-2A>G splice-site mutation (19 of 10,953 patients in TCGA across all tumor types) and a p.M1?" (PMID 32494760, 2020). "For example, B2M could induce resistance to tipifarnib by inducing tumor cell survival, aggressiveness, and EMT via the induction of RAS-independent activation of the phosphoinositide 3-kinase (PI3K)/AKT/mammalian target of rapamycin (mTOR) and ERK signaling pathways." (PMID 32460812, 2020). "Furthermore, the relative increase in the transcriptional and translational expression level of insulin-like growth factor-binding protein 7 (IGFBP7), midkine (MDK), and beta-2-microglobulin (B2M) genes was observed in remnant tumor cells after tipifarnib treatment." (PMID 32460812, 2020). "However, the implications of somatic HLA and B2M mutations have not been fully explored in the context of antigen presentation via the MHC-I molecule during tumor development." (PMID 31345234, 2019). "Loss of B2M resulting in reduced cell surface MHC-I molecules should reduce the ability of tumor cells to inhibit NK cell driven cytotoxicity, however it is unclear whether this would affect NK cell levels in the tumor." (PMID 31345234, 2019). "Percentage distribution of tumor stages for the patients with or without B2M and HLA mutations." (PMID 31345234, 2019). "Hence, to clarify the potential effect on tumor development of MSCs-derived B2M in vivo, we subcutaneously injected 1 × 106 ESCC cells either alone or in combination with the same amount of MSCs into nude mice and observed the formation of xeno-transplanted tumors." (PMID 29615660, 2018). "From this finding, we concluded that B2M mutations do not provide an additional advantage in the state of immunosuppression as there is, for obvious reasons, no genetic pressure for immune escape on the tumor cells." (PMID 29564225, 2018). "The presence of B2M in the CSF may be a CNS inflammatory or tumor marker." (PMID 30114292, 2018).
tumor (continued). "This indicates that there may be B2M-independent mechanisms for T-cells to recognize the tumor cells and that B2M loss alone is not a good predictive marker for ACT response." (PMID 29170503, 2017). "We conclude that in addition to genetic mutations leading to loss of B2M (e.g., Pat208), other non-genetic mechanisms also use by tumor cells (e.g., Pat99 and Pat25) and may lead to transient or long-term reduction in antigen presentation." (PMID 29070816, 2017). "Using the OMIQ platform and CyTOF, they characterized tumor immune infiltration and found that MC38 and YUMMER2.1 cells with B2M KO responded to anti-PD-1 treatment alone or in combination with IL-2 agonists, mediated by CD4+ T cells and NK cells." (PMID 40191187, 2025). "The small tumor foci expressing both TSPY and B2m were capable of forming TSPY-peptide-MHC-I complexes on the cell surface and were targeted by the cytotoxic T cells and immune elimination." (PMID 40563082, 2025). "Engineered exosomes expressing SIRPα, PD-1, and LILRB1 interact with receptors on tumor cells (CD47, PD-L1, and B2M), promoting the phagocytosis of tumor cells and enhancing antigen presentation by immune cells." (PMID 39465690, 2025). "Then we conducted rescue experiments on tumor cells that had knocked out circGRAMD4, RBM4 and NBR1 by knocking out B2M again to reduce the expression level of MHC-I on the cell surface." (PMID 40373256, 2025). "B2M/TCR/PD-1 KO can reduce immunogenicity, prevent GvHD, and significantly enhance the anti-tumor activity of CAR-T cells." (PMID 40191187, 2025). "We found that the elevated MHC-I levels on tumor cells surface after knocking out circGRAMD4, RBM4, and NBR1 decreased again with the knockout of B2M, and the corresponding changes in cancer cell death and CD8+ T cytokine levels also occurred." (PMID 40373256, 2025). "In the context of B2M KO, the activation of CD4+ T cells and NK cells can overcome resistance to PD-1 blockade therapy to enhance anti-tumor efficacy." (PMID 40191187, 2025). "The fraction of dead tumor cells increased to ~71% for YT–Vav1+CISH–/– and to ~58% for YT–Vav1+B2M–/– (p=0.01 and p=0.025, respectively, compared to the control with no exposure)." (PMID 40071076, 2025). "Guide RNAs were employed to delete B2m, Jak1, or Psmb9 genes in ICB-responsive EMT6 murine tumor cells." (PMID 38427670, 2024). "Tumor cells that were treated with EZH2 inhibitor alone or in combination with anti-PD1 had increased H2-K1, B2m, and Ifngr1 expression, and decreased expression of neutrophil-recruiting chemokines such as Cxcl3, Cxcl5, and Ppbp (a.k.a Cxcl7)." (PMID 38265267, 2024). "Among that, the protein expression of IGF2BP3, B2M, CD36, CDKN1A, ANKRD33B, and LHFPL2 were up-regulated; However, the protein expression of APP and CTDSPL was low in both normal and tumor tissues." (PMID 39470474, 2024). "With respect to the within-group distribution, some genes have a narrow expression range (for example, KRT, HIF1A in both tumour and stromal compartments of p16+/HPV+ tumours, and PSMB10, B2M in the stromal compartment for all p16/HPV subgroups)." (PMID 39328208, 2024). "In contrast, the disruption of B2m in B16OVA cells attenuated the antitumor effect mediated by OT-I T cells, rendering the combination treatment with BLM ineffective in slowing tumor growth." (PMID 39106105, 2024). "Areas annotated as having diffuse immune infiltration showed higher levels of MHCI (beta-2-microglobulin, B2M) and checkpoints IDO1, PD-L1, PD-1 and Tim-3 in tumor AOIs, and higher levels of T-cells (CD3) and Granzyme B in immune AOIs." (PMID 39026018, 2024). "Similar effects on tumor infiltration of both MDSC populations, effector CD4+ T cells, CD4+ Tregs, and NK cells were observed in MC38 B2m KO tumors." (PMID 38427670, 2024). "Significant ilQTLs, the majority of which of somatic origin, were identified in immune-relevant genes, including B2M, HLA genes, CANX, LDHA, PSMB2, and HNRNPR, which are known to affect the tumor immune landscape." (PMID 38773080, 2024).